LINC00589 (long independently transcribed non-coding RNA 589)
Synonyms: TSLNC8; C8orf75
Gene: Long non-coding RNA gene on chromosome 8 (29,654,314 to 29,770,539, reverse strand). Ensembl gene ENSG00000251191.
Diseases named in the same sentence as LINC00589 in open-access papers:
LINC00589 is named in the same sentence as 11 diseases in open-access papers, as found by Europe PMC text mining. Sharing a sentence is not in itself a finding about the gene and the disease. The quoted sentences say what the papers report.
hepatocellular carcinoma (7 papers, 2020 to 2024). A malignant tumor that arises from hepatocytes. "LINC00589, also known as TSLNC8, prevents the growth, invasion, and metastasis of glioma, non-small cell lung cancer, and hepatocellular carcinoma." (PMID 39170516, 2024). "Although LINC00589 has been reported to suppress cell proliferation in hepatocellular carcinoma and non-small cell lung cancer, its biological roles are largely unknown." (PMID 36309503, 2022).
melanoma (5 papers, 2022 to 2023). A malignant, usually aggressive tumor composed of atypical, neoplastic melanocytes. "LINC00589 has emerged as a critical mediator of drug resistance in multiple cancer types, including lung cancer 27, melanoma 25, and HER2-positive breast cancer." (PMID 37781073, 2023). "Notably, in melanoma 25, the upregulation of LINC00589 has been demonstrated to restore sensitivity to the BRAF inhibitor PLX4720 in resistant cells, offering a potential therapeutic avenue for patients resistant to BRAF inhibitors." (PMID 37781073, 2023).
breast carcinoma (3 papers, 2022 to 2024). "In this study, we evaluate the expression of LINC00589 in trastuzumab-resistant breast cancer tissues and cell lines, and analyze its association with patient prognosis." (PMID 36309503, 2022). "To determine the functional role of LINC00589 in trastuzumab resistance of HER2-positive breast cancer cells, we constructed lentiviruses that overexpress or silence LINC00589." (PMID 36309503, 2022). "Here, we identified the long noncoding RNA, LINC00589 as a key regulatory node for concurrent intervention of these processes in breast cancer cells in vitro and in vivo." (PMID 36309503, 2022). "Furthermore, Kaplan–Meier analysis indicated that HER2-positive breast cancer patients with high LINC00589 expression had a better overall survival than those with low LINC00589 expression." (PMID 36309503, 2022). "The expression of LINC00589 also reversed cancer stem cell-like properties and reduced chemoresistance in HER2-positive breast cancer." (PMID 37781073, 2023). "Thus, LINC00589 is a key node for simultaneously controlling trastuzumab resistance, MDR, and CSC-like properties in breast cancer with potential therapeutic value." (PMID 36309503, 2022). "CCK-8 assays revealed that overexpression of LINC00589 decreased the cell viability of all the six TR SKBR3 cells, while knockdown of LINC00589 increased cell viability in WT SKBR3 and BT474 breast cancer cells, which was verified under increasing doses or times of trastuzumab treatment." (PMID 36309503, 2022). "Nevertheless, the role of LINC00589 in breast cancer has not been elucidated." (PMID 36309503, 2022). "Meanwhile, LINC00589 overexpression could not change HER2 expression at both mRNA and protein levels in trastuzumab-resistant breast cancer cells." (PMID 36309503, 2022).
lung carcinoma (2 papers, 2022 to 2023). "Similarly, LINC00589 acts as a modulator, enhancing the efficacy of osimertinib in suppressing the progression of lung cancer." (PMID 37781073, 2023).
tumor (11 papers, 2020 to 2024). "Multiple research teams have investigated the functional implications of LINC00589 up-regulation and/or silencing on tumor development using xenograft models." (PMID 37781073, 2023). "Similar to in vitro studies, both oncogenic and tumor suppressor role have been reported for LINC00589." (PMID 37781073, 2023). "Abnormal expression of LINC00589 has shown significant correlations with tumor development, including tumor grade, lymph node and distant metastasis, and tumor stage." (PMID 37781073, 2023). "Consistent with our in vitro results, LINC00589 overexpression significantly decreased the tumor volume and weight; however, either miR-100 or miR-452 reversed the repressive effect of LINC00589 on tumor volume and weight in nude mice." (PMID 36309503, 2022). "Additionally, LINC00589 overexpression promotes tumor apoptosis and inhibits metastasis by activating autophagy and suppressing the EMT." (PMID 37781073, 2023). "Thus, LINC00589 may serve as both a tumor suppressor and a tumor promoter according to different cancer pathological settings." (PMID 36309503, 2022). "Moreover, IHC assay data in xenograft tumor tissues revealed that LINC00589 overexpression could upregulate the protein expressions of DLG5 and PRDM16, while miR-100 and miR-452 abrogated the promotion of LINC00589 on the DLG5 and PRDM16, respectively." (PMID 36309503, 2022).
cancer (2 papers, 2022 to 2023). A tumor composed of atypical neoplastic, often pleomorphic cells that invade other tissues. "Animal models have provided evidence regarding the impact of LINC00589 modulation on different cancer types." (PMID 37781073, 2023). "Collectively, these results indicate that LINC00589 regulates trastuzumab resistance, cancer stem cell-like properties and multiple chemoresistance, at least in part, by modulating DLG5 and PRDM16 expression." (PMID 36309503, 2022). "However, LINC00589 also interacts with HUR and stabilizes CTNNB1 mRNA, thereby promoting cancer progression in pancreatic cancer." (PMID 36309503, 2022).
LINC00589 also shares sentences with these, for which no sentence is quoted: glioma (3 papers); gastric cancer (1); liver cancer (1); non-small cell lung carcinoma (1); pancreatic cancer (1).